Y_RNA (Y RNA )
Gene: Miscellaneous RNA gene on chromosome 7 (74,895,816 to 74,895,917, forward strand). Ensembl gene ENSG00000239069.
Homologues: Orthologues: chimpanzee Y_RNA (99% identical), pig Y_RNA (75% identical). Paralogues in human: Y_RNA (100% identical), Y_RNA (97% identical), Y_RNA (93% identical), Y_RNA (92% identical), Y_RNA (90% identical), Y_RNA (89% identical), Y_RNA (87% identical), Y_RNA (85% identical), RNY3 (84% identical), RNY3P12 (84% identical), Y_RNA (84% identical), RNY3P1 (83% identical), and 98 more.